TTF1 (transcription termination factor 1)
Diseases named in the same sentence as TTF1 in open-access papers (continued):
Sharing a sentence is not in itself a finding about the gene and the disease.
lung carcinoma (continued). "MYBPH is a transcriptional target of TTF-1, a master regulator of lung development that acts as a lineage-survival oncogene in the formation of lung cancer." (PMID 37664033, 2023). "Thyroid transcription factor 1 (TTF-1) is selectively expressed in lung and thyroid cancers and is extremely uncommon in other kind of cancers, which makes it as a useful biomarker for lung cancer." (PMID 36499466, 2022). "The knockdown of TTF-1 inhibits cancer growth, and it has also been reported that the manipulation of the TTF-1 promoter to express miR-7 can inhibit the growth of human lung cancer cells." (PMID 36614938, 2022). "Of these 3, TTF1 had the largest OR at 54.3, which means that if a given lung cancer sample is positive for TTF1, the odds of it being primary are 54.3 times more than the odds of it being non-primary." (PMID 35027072, 2022). "The lung cancer history of the patient formed a basis for analysis of TTF-1 as well as napsin A biomarkers in paraffinized specimens." (PMID 35558388, 2022). "Expression of CK7 is positive in cancers of the lung, breast, ovary, pancreas, thyroid, and salivary gland, whereas expression of TTF-1 is characteristic of primary lung cancer and thyroid cancer." (PMID 36039229, 2022). "TTF-1 is well-known to be a transcription factor that is highly expressed in thyroid, brain and lung cancer." (PMID 36459241, 2022). "Thyroid transcription factor (TTF-1) and napsin A were performed owing to the lung cancer history and positive results were obtained, indicating lung cancer metastasis." (PMID 35558388, 2022). "Immunohistochemistry (IHC) has always been pivotal in unveiling the diverse cell differentiation lineages present in lung cancer by using specific biomarkers such as TTF1 and p63/p40, which closely reflect the relationship between genotype and phenotype.." (PMID 36712764, 2022). "Both the gastric tumor biopsy and gastrectomy specimens were TTF-1 (+), suggesting that the gastric tumor was metastasis from lung cancer." (PMID 36459241, 2022). "A large number of studies have shown that TTF-1 plays a vital role in the occurrence of lung cancer." (PMID 34631891, 2021). "Most tumors exhibited features of lung cancer histologically and molecularly, as demonstrated by expression of TTF1 marker, with higher tumor burdens in SPK than in PK mice." (PMID 34381046, 2021). "Cross-species analysis and the function experiments identified that the TTF-1 inhibits the differentiation and metastatic potential of lung cancer in vivo." (PMID 34631891, 2021). "In terms of mechanism, studies have shown that TTF-1 can regulate the growth and metastasis of lung cancer cells through a variety of downstream target genes, including Selenbp1, EGFR, Foxa2, CDX2, and DDB1." (PMID 34631891, 2021). "The specific IHC pattern of CK7+/CK20- with a positive thyroid transcription factor-1 (TTF1) stain was commonly encountered and was confidently diagnosed as lung cancer in almost all cases." (PMID 33747958, 2021). "In other studies, TTF-1 has been proposed to be a candidate lineage lung oncogene, knockdown of it reduced growth, and cell viability of lung cancer containing the TTF-1 amplicon." (PMID 33585516, 2020). "Its expression has been shown to be useful in combination with TTF-1 in differentiating primary lung carcinoma from pulmonary metastases of extra-thoracic origin." (PMID 31330946, 2019). "For the six other cases, we used antibodies to eliminate a metastasis of a carcinoma (anti-AE1/AE3 antibody) or of thyroid or lung carcinoma (anti-TTF1 antibody)." (PMID 31805712, 2019). "Anaplastic lymphoma kinase (ALK)-rearranged lung cancers are most often TTF-1 positive tumors, characterized by an acinar pattern with mucin/signet-ring cell morphology." (PMID 31330946, 2019).
lung carcinoma (continued). "We thus investigated the relationship of IL-35+ and TTF-1+PD-L1+ cells in the setting of lung cancer." (PMID 30956278, 2019). "Considering the fact the platinum compounds remain a widely used chemotherapy for lung cancer in the era of targeted and immunotherapies, we were particularly interested in understanding the mechanism of TTF-1-induced sensitization to cisplatin." (PMID 31142791, 2019). "In short, this study highlights the enigmatic activities of TTF-1 in lung cancer, and calls for future research to optimally manage chemotherapy of patients with TTF-1+ lung ADs." (PMID 31142791, 2019). "In the present study, we retrospectively examined consecutive small lung biopsies performed for lung cancer and used TTF1 and p63 as the main markers for ADC and SQCC, respectively." (PMID 30379223, 2018). "Regarding morphology, tumors in our model appeared to be papillary carcinomas, all TTF-1 and cytokeratin-7 positive analogous to human lung cancers." (PMID 29415661, 2018). "In appropriate clinical context, the prostate-specific antigen (PSA) for prostate cancer, PAX8 for ovarian cancer, alphafetoprotein for liver cancer, and TTF1 for lung cancer can be reliably used as a single marker." (PMID 29116378, 2018). "Most recently, our group first tried to construct a eukaryotic vector of promoter of TTF-1 gene-operating expression of miR-7 (termed p-T-miR-7) and observed its effects on the growth and migration of human lung cancer cells in vivo." (PMID 29858085, 2018). "The lung cancer cell line study of knockdown and overexpression of TTF-1 revealed TTF-1 mediated High Mobility Group AT-Hook 2 (HMGA2) protein involved with epithelium-mesenchymal transformation." (PMID 29079814, 2017). "Combining these results demonstrated that TTF-1-promoter-operating miR-7 expression affected the growth and metastasis of human lung cancer cells through NDUFA4." (PMID 28325285, 2017). "It is the first time the potential value of the TTF-1 promoter operating distinct miRNAs expression in targeted gene therapy against lung cancer has been explored." (PMID 28325285, 2017). "Next, we further monitored the impact of TTF-1-promoter-operating miR-7 expression on lung cancer cells in vivo." (PMID 28325285, 2017). "Here, we first evaluated the efficacy of miR-7 expression operated by the promoter of TTF-1, a lineage-specific oncogene in lung cancer, in vitro using an eukaryotic vector of TTF-1-promoter-operated expression of miR-7 (termed as p-T-miR-7)." (PMID 28325285, 2017). "As IASLC/ATS/ERS emphasized in the new classification in 2011, immunohistochemical (including TTF-1), combined with histochemical and molecular studies were suggested to determine the specific type of lung cancer." (PMID 29296178, 2017). "In summary, the subsets shown here can be identified clinically using an established, standard-of-care for lung cancer, biomarker (TTF1) or a marker routinely used in other cancers such as breast cancer (cMYC)." (PMID 29088717, 2017). "In human lung cancer, the expression of TTF-1 and GM-CSF exhibits a statistically significant and positive correlation." (PMID 26912193, 2016). "Immunophenotypic analysis including TTF-1 is crucial to establish the diagnosis of breast metastasis from primary lung cancer." (PMID 27488410, 2016). "Our interest in exploring how TTF-1 modulates the proteinaceous secretome of lung cancer cells motivated us to initiate this study by first conducting a focused qPCR profiling of cytokine expression between TTF-1-on/off states." (PMID 26912193, 2016). "Because TTF-1 expression status is frequently analyzed in the clinics for human lung cancer, any new understanding of TTF-1 biology will likely inspire follow-up research to improve clinical practices." (PMID 26912193, 2016). "Our observation that TTF-1 increases the abundance of VEGF in the lung cancer secretome predicts that the EDM of TTF-1+ cells, which contains the bulk of TTF-1-induced VEGF, would likely be proangiogenic." (PMID 26912193, 2016).
lung carcinoma (continued). "Surprisingly, the EDM of TTF-1+ lung cancer cells (designated EDM-TTF-1+) displayed an anti-angiogenic activity in the endothelial cell tube formation assay." (PMID 26912193, 2016). "By IHC assay, we found that Cd68 positive macrophages were also strongly stained by Spp1, whereas Ttf1-positive lung cancer cells were only weakly stained positive for Spp1." (PMID 26565418, 2015). "By IHC assay, we found that both the Ttf1-positive lung cancer cells and Cd68-positive macrophages were stained positive for Cxcl13, but Ttf1-positive cells constituted more than 95% of the cellular component of the lung tumor tissues of the mice." (PMID 26565418, 2015). "Another aspect of TTF-1-expression is a potentially possible predictive value on overall survival of lung cancer patients." (PMID 25889870, 2015). "In lung cancers, Jerome and colleagues had reported that the rates of positive TTF-1 expression in adenocarcinoma, small cell carcinoma, and nonmucinous bronchio-alveolar carcinoma were 90%, 80%, and 100%, respectively." (PMID 25947890, 2015). "An important role in the regulation of HMGA2 expression in lung carcinomas seems to be played by TTF-1." (PMID 25859543, 2015). "Herein, we summarize the role of this transcription factor in the development, diagnosis, and prognosis of lung cancer in the hope of providing insights into the utility of TTF-1 as a novel biomarker of lung cancer." (PMID 24949691, 2014). "It's well known that thyroid transcription factor 1 (TTF-1) was a special lineage-survival oncogene in lung cancer according to recent researches." (PMID 24949691, 2014). "Thus protein expression and DNA amplification of TTF-1 have divergent implications in patients with lung cancer and a clearer understanding of this phenomenon would further clarify the significance of the association between certain driver mutations and the expression of the TTF-1 protein." (PMID 25594059, 2014). "TTF-1 is another lung cancer marker and one that ∼68% of adenocarcinomas and 25% of squamous cell lung carcinomas have been shown to stain positively for." (PMID 24137345, 2013). "The most useful immunohistochemical stains to differentiate gastrointestinal carcinoma from lung carcinoma are TTF-1, cytokeratin 7, cytokeratin 20, CDX2, and villin." (PMID 23119210, 2012). "Small bowel metastases from primary lung cancer were usually confirmed by pathological analysis, with the help of immunohistochemical staining of TTF-1, CDX2, CK7 and CK20, to differentiate the primary small bowel tumor from metastases of lung cancer." (PMID 22284720, 2012). "In the current study, we found that overexpressed TTF-1 downregulated the expression of Ki-67, a marker of cell proliferation, and induced apoptosis of lung cancer cell line A549." (PMID 22940844, 2012). "In the present study, we demonstrated very low frequency of TTF-1 mRNA expression in human lung cancer cell lines." (PMID 22940844, 2012). "There have been a few conflicting reports on the prognostic value of TTF-1 overexpression in lung cancer patients." (PMID 22940844, 2012). "Only the mRNAs level of MGH24, H125 and RVH6849 showed overexpression while other 7 NSCLC cell lines lowered or lacked the expression of TTF-1 mRNA, which was consistent with the previous reports on TTF-1 expression in lung cancer cell lines." (PMID 22940844, 2012). "Gain at 14q13 has been studied in relation to lung cancer, and co-amplification and overexpression of the transcription factors TTF-1, NKX2-8, and PAX9 (all located at 14q13) have been associated with cisplatin resistance in lung cancer cell lines." (PMID 21858162, 2011). "This is of great interest for thyroid or lung cancers where TTF-1 expression is crucial to maintain cell differentiation." (PMID 21814573, 2011).
lung carcinoma (continued). "In neoplastic tissues, TTF-1 is used as a marker of differentiation in thyroid and lung carcinomas and has been widely used to discern the primary site of thyroid and lung tumour origin in patients with metastatic disease." (PMID 21814573, 2011). "In fact, despite their relatively bland appearance, the presence of CK7 and TTF-1 positive glandular structures within the pleura raised concern for an occult lung carcinoma." (PMID 17603877, 2007). "TTF-1 is a well-known marker in the diagnosis of lung cancer, especially in ADC and SCLC." (PMID 39941799, 2025). "Our study examines another protein called Thyroid Transcription Factor-1 (TTF-1) to see if it could help predict outcomes in lung cancer patients treated with immunotherapy." (PMID 40647486, 2025). "TTF-1 has been reported to be associated with lung cancer development; hence, TTF-1 is expressed in 60–80% of the cases of non-squamous non-small cell lung cancer (non-Sq NSCLC) and is commonly used for the histological diagnosis of lung cancer." (PMID 39076994, 2024). "Immunostains TTF-1 and p63 were done on 206 and 46 of 234 (lung cancer) patients respectively." (PMID 39570822, 2024). "TTF1 is also an important marker positive in 80% of lung cancers, although it may also be positive in thyroid tumors." (PMID 39292386, 2024). "Additionally, a minimal panel of immunohistochemical markers, including napsin A, TTF-1, p63, and synaptophysin, was used to subclassify lung carcinomas." (PMID 39070322, 2024). "In the present study, we investigated if there may be alternatives to the panel CDX2, CK7, CK20, and TTF-1 for differentiation between primary lung cancer and pulmonary metastases from the GI tract." (PMID 37349623, 2024). "The most common immunostains used in lung cancer BM workups are TTF-1, cytokeratin 7 (CK7) and p63." (PMID 39570822, 2024). "Based on the latest studies, recommendations for the best practical usage of IHC in lung cancer diagnosis considered Thyroid Transcription Factor 1 (TTF‐1) when it is detected by 8G7G3/1 monoclonal antibody and p40 as the best biomarkers for NSCLC subtypes but are not considered as diagnostic." (PMID 39300939, 2024). "Therefore, TTF-1 has been considered as a putative sensitivity biomarker to statins in human lung cancer." (PMID 39329956, 2024). "Among these genes, TTF1 was demonstrated to contribute to the maintenance of the function of terminal respiratory unit cells, and is used in immunohistochemistry differential diagnosis of lung cancer." (PMID 38248716, 2023). "TTF1 is a marker currently used in routine clinical practice to distinguish lung cancer metastases." (PMID 38008767, 2023). "When examined by organ, although the frequency varies among reports, TTF‐1 is reported to be positive in 76.7% of adenocarcinomas, 87.6% of small cell carcinomas, 4% of squamous cell carcinomas, and 39.6% of large cell carcinomas among lung cancers." (PMID 37261050, 2023). "Although the number of cases is limited, this study also shows that TTF-1+ CTCs may be a potential biomarker for lung cancer." (PMID 36499466, 2022). "However, extensive p63 and p40 expression with focal TTF-1 in the same tumor cell population is extremely rare among lung carcinomas, and NC should be considered." (PMID 36290813, 2022). "So far, only limited studies have demonstrated a correlation between TTF-1+ CTCs and lung cancer." (PMID 36499466, 2022). "Indeed, we found that the expression level of TTF-1 in lung cancer tissue is higher than that in normal lung tissue." (PMID 35371324, 2022). "However, the role of TTF1 in lung cancer pathogenesis and its relationship with the ALK translocation status is unclear." (PMID 32876329, 2021). "Therefore, TTF-1 is currently of great value in the diagnosis and differential diagnosis of lung cancer, but its possibility as a prognostic marker needs further research to be clarified." (PMID 34631891, 2021).
lung carcinoma (continued). "However, the mechanism of TTF-1 in regulating the occurrence of different types of lung cancer remains to be further explored." (PMID 34631891, 2021). "Interestingly, some studies have shown that TTF-1 can inhibit the growth of lung cancer and plays a double-edged role in the occurrence and development of lung cancer." (PMID 34631891, 2021). "There are promising biomarkers for lung cancer diagnosis, such as TTF1 (thyroid transcription factor 1), folate receptor-positive circulating tumor cells, but no lncRNAs are ready for broad clinical application, which calls for more exploration into the function and mechanism of lncRNAs." (PMID 31901898, 2020). "Given the fact that TTF-1 immunoreactivity is routinely analyzed for lung cancer patients, hopefully the results described herein inspire others to comprehensively investigate how TTF-1 modulates chemotherapeutic responses and translate the findings to improve lung cancer management." (PMID 31142791, 2019). "Moreover, immunohistochemical staining showed that these lesions were positive for poorly differentiated colon cancer markers (CK20, CDX2, AE1/AE3), and lung cancer markers (TTF1 and Napsin)." (PMID 31200749, 2019). "Much research has been conducted to investigate roles of TTF-1 in lung cancer biology." (PMID 31142791, 2019). "Presently, whether the expression of TTF-1 is related to the prognosis of lung cancer remains controversial." (PMID 31620365, 2019). "Moreover, we further evaluated the potential effect of the TTF-1-promoter-operating miR-7 expression on the growth and metastasis of human lung cancer cells in vivo." (PMID 28325285, 2017). "Consistently, we found that the expression level of TTF-1 was also higher in lung cancer cells than that in other cancer cells, which was consistent with previous finding that TTF-1 was dominantly expressed in lung cancer cells, but not other types of cancer cells." (PMID 28325285, 2017). "Of note, we found that overexpression of NDUFA4, a novel target molecule of miR-7, could abrogate the effect of TTF-1-promoter-operating miR-7 expression on the growth of lung cancer cells, accompanied with altered expression of phosphorylation of Akt and Erk." (PMID 28325285, 2017). "TTF1 (used in the diagnosis lung cancer) could therefore be used as a surrogate of DLL3 expression to identify patients who may respond to the DLL3 antibody-drug conjugate rovalpituzumab tesirine." (PMID 29088717, 2017). "We first observed that TTF-1 promoter could effectively operate miR-7 expression in lung cancer cells." (PMID 28325285, 2017). "Therefore, in this present study, we first constructed an eukaryotic vector of promoter of TTF-1-gene-operating expression of miR-7 (termed as p-T-miR-7) and observed its effects on the growth and migration of human lung cancer cells in vitro." (PMID 28325285, 2017). "In summary, we take the data reported herein as the evidence that TTF-1 may reprogram the function of lung cancer secretome." (PMID 26912193, 2016). "The cytospins were immunostained with cytoplasmic or nuclear markers typically used in clinical practice: cytokeratin AE1/AE3 for carcinomas, melanoma-associated antigen recognized by T cells (MART-1) for melanoma, and thyroid transcription factor 1 (TTF1) for lung carcinoma." (PMID 26999048, 2016). "To explore how wt-TTF-1 (referred to as TTF-1 hereafter) modulates lung cancer secretome, we used a commercial qPCR array that targets 84 cytokines (Qiagen) to profile the RNA expression changes of the TTF-1 inducible system before and after turning on TTF-1 expression." (PMID 26912193, 2016). "In light of our findings, it is tempting to suggest that the antiangiogenic secretome of TTF-1+ lung cancer cells may contribute to the well-documented, better clinical outcome of TTF-1+ lung ADs." (PMID 26912193, 2016). "TTF-1 has a specificity of 100% and sensitivity of 85% in canine primary lung cancer." (PMID 26560147, 2015).